MTOR (mechanistic target of rapamycin kinase)
Diseases named in the same sentence as MTOR in open-access papers (continued):
Sharing a sentence is not in itself a finding about the gene and the disease.
melanoma (continued). "In all examined melanoma cell lines, inhibitors:: AKT – MK-2206 (2 μM), MEK – AS-703026 (10 μM), PI3K – LY294002 (20 μM), ERK1/2 – U0126 (10 μM), mTOR – everolimus (20 nM, 2 μM, 5 μM and 10 μM) showed no cytotoxicity effect in the 24 h of treatment." (PMID 30848427, 2019). "In cultured melanoma cells lacking detectable LKB1 expression (IGR37), membrane binding of LKB1 is essential for efficient AMPK (and MARK) activation, suppression of mTOR and cell survival under energetic stress." (PMID 28649994, 2017). "Toxicity from TKI or mTOR inhibitors for RCC and from chemotherapy, BRAF inhibitors or anti-CTLA-4 antibodies for melanoma are low-grade but continuous and exert a negative impact on quality of life." (PMID 25245327, 2014). "Our results suggest that most BRAFV600E mutant melanomas not responding to vemurafenib are also cross-resistant to single agent MEK inhibitors, but co-targeting of the AKT/mTOR pathway provides means of treating most of these resistant cells." (PMID 22194965, 2011). "Moreover, the mentioned mTOR/ PI3K/AKT pathway plays an important role in the case of skin cancers, both melanoma and non-melanoma, as a prognostic factor and therapeutic target." (PMID 40710294, 2025). "However, in high-OXPHOS melanomas, MITF is not suppressed by HIF1α but is promoted by the mammalian target of rapamycin (mTOR), leading to the transcription of PGC1α, a transcriptional coactivator which induces the expression of different OXPHOS genes." (PMID 33498757, 2021). "Despite the active state of the PI3K/mTOR pathway, to date, studies of CCI-779 in melanoma have not shown promise, indicating that discovery and exploitation of novel survival pathways and mechanisms of resistance would be necessary for further successful development of this agent." (PMID 23383069, 2013). "When rictor was immunoprecipitated in A375 melanoma cells, BRAF was detected in the rictor complex, in addition to mTOR and sin1 (core components of mTORC2), but not raptor (a component of mTORC1), suggesting that BRAFV600E may interact with mTORC2 directly." (PMID 22880048, 2012). "However, USP22 inhibition could not further enhance the inhibitory effect on melanoma invasion in the presence of PI3K inhibitor (GDC‐0941), Akt inhibitor (MK‐2206), or mTOR inhibitor (CCI‐779)." (PMID 39135915, 2024).
glioblastoma (598 papers, 2008 to 2026). The most malignant astrocytic tumor (WHO grade IV). "Fingolimod also inhibits the PI3K/Akt/mTOR/p70 S6K signaling pathway, thereby reducing the migration and invasion of human glioblastoma cell lines, the primary cause of death in glioblastoma patients." (PMID 40723894, 2025). "Inhibiting the PI3K/AKT/mTOR pathway is a promising strategy against glioblastoma, as AKT3 expression is associated with GSC aggressiveness." (PMID 40867215, 2025). "Another important hallmark of glioblastoma to promote proliferation was shown to be the hyperactivation of the PI3K (Phosphatidylinositol 3-kinase)/AKT (Ak-strain Thyoma)/mTOR (mammalian Target Of Rapamycin) pathway." (PMID 38378853, 2024). "The dysregulation of the mTOR pathway is a hallmark of glioblastoma and plays a critical role in tumor growth and progression." (PMID 37834408, 2023). "The review aims to emphasize the molecular mechanisms underlying mTOR dysregulation in glioblastoma, including the impact of genetic alterations and upstream signaling pathways." (PMID 37834408, 2023). "The dysregulation of mTOR commonly occurs in glioblastoma, and researchers have linked its activation to tumor cell survival, angiogenesis, invasion, and resistance to conventional therapies." (PMID 37834408, 2023). "Activation of the PI3K/AKT/mTOR pathway is associated with poor prognosis in glioblastoma (GBM) patients." (PMID 37592783, 2023). "Given glioblastoma’s propensity to develop resistance to therapies, it becomes essential to identify biomarkers associated with resistance to mTOR inhibitors." (PMID 37834408, 2023). "PI3K signaling, one of the upstream activator of mTOR, is known to be activated in glioblastoma by genetic mutations or deletions." (PMID 38065968, 2023). "The dysregulation of the mTOR pathway is a prominent hallmark in glioblastoma, substantially contributing to various facets of tumor development and pathogenesis." (PMID 37834408, 2023). "More than 60% of glioblastoma cases have been linked with at least one mutated or dysregulated PI3K-Akt-mTOR pathway proteins." (PMID 35022057, 2022). "Treatment with apigenin caused G2/M arrest in glioblastoma cells and decreased levels of Akt, mTOR, ERK, STAT3, and S6K proteins." (PMID 36193062, 2022). "In glioblastoma, DGKα has been associated with tumor proliferation via regulation of mTOR expression and activity." (PMID 36358678, 2022). "Temozolomide mainly leads to mutations in retinoblastoma (RB) and AKT/mammalian target of rapamycin (mTOR) signaling, which plays a critical role in glioblastoma tumor growth and metastasis." (PMID 33806782, 2021). "The PI3K/mTOR canonical pathway showed genomic alterations in 76% of IDH-wild-type glioblastoma cases, mainly through PTEN mutations in 53% of cases." (PMID 34572759, 2021). "Mechanistic target of rapamycin (mTOR) signaling is found to be upregulated in tumor-associated microglia in response to glioblastoma cell stimulation, as well as in microglia in response to a LPS challenge." (PMID 34082793, 2021). "Second, PTEN mutations that weaken its inhibitory effect on Akt/mTOR signaling are frequently found in many tumors including glioblastoma, which causes more complicated modulation of Akt/mTOR pathway in glioblastoma, compared with normal neurons." (PMID 31849609, 2019). "Through immunoprecipitation, we found that SEMA3F inhibits the association between mTOR, raptor and rictor in glioblastoma cells, suggesting an inhibitory effect on both mTORC1 and mTORC2, respectively." (PMID 30532711, 2018). "In glioblastoma harboring PI3K/mTOR activation due to PTEN deficiency, combined inhibition using the SMO inhibitor LDE225 and the PI3K inhibitor BKM120 was necessary to reduce cell viability and inhibit tumor growth." (PMID 25749378, 2015).
glioblastoma (continued). "The recent categorization of glioblastoma subtypes is an important tool in identifying tumors that are more susceptible to mTOR targeting." (PMID 22530122, 2012). "Involved in various signaling pathways implicated in glioblastoma, mTOR plays a role in a number of cellular processes, including cell proliferation and growth, angiogenesis." (PMID 20652056, 2010). "A great number of studies on Akt pathway, which in its expanded version includes phosphatidylinositol 3-kinase (PI3K)/Akt/rapamycin-sensitive mTOR-complex (mTOR) signaling have reported the frequency of mutations and copy number aberrations of its components in glioblastoma to be around 88%." (PMID 38672638, 2024). "Proteomic signatures linked to the mTOR pathway might be potential biomarkers for glioblastoma prognosis." (PMID 37834408, 2023). "Frequent PTEN mutations in glioblastomas lead to a blockade of this inhibition and a complete activation of this signaling pathway with its main effector molecule, the serine/threonine kinase mTOR (mammalian target of rapamycin)." (PMID 37626776, 2023). "Therefore, we suggest that stellettin B inhibits glioblastoma cell migration through the inhibition of Akt/mTOR signaling, causing downstream Girdin inactivation, which leads to downregulation of F-actin polymerization in glioblastoma cells." (PMID 30769863, 2019). "In addition, GEM mouse models with deficiencies in the FAO, LAL or mTOR pathway would establish valuable models to investigate the in vivo metabolic and pathological roles of each component of these pathways in glioblastoma." (PMID 31225500, 2019). "In addition, cathepsin S-induced inhibition of the PI3K/AKT/mTOR/p70S6K signaling pathway was found to cause autophagy in human glioblastoma cell lines." (PMID 29467620, 2018). "In this study, we investigated the effects of XHP on human U-87 MG glioblastoma cell growth and its underlying mechanisms related to ROS-mediated Akt/mTOR/FOXO1 pathway, so as to provide some experimental data to the further research and development on antiglioblastoma application of XHP." (PMID 30046342, 2018). "Furthermore, the mTOR pathway has been demonstrated to be a key modulator in glioblastoma cell proliferation and is implicated in cancer pathogenesis." (PMID 28891980, 2017). "To confirm whether mTOR signaling is affected in IDH1-mutated glioblastoma cells, we performed western blot analyses for p-mTOR and its downstream effector p-S6." (PMID 29057925, 2017). "Epithelial growth factor receptor (EGFR) in connection with the phosphoinositol-3 kinase (PI3K) pathway signaling, as well as the association between the EGFR and the mTOR signaling pathway, appears important to maintaining the life of glioblastoma multiforme cells." (PMID 24940426, 2014). "EGFR gene mutations activating mTOR have been studied in colorectal cancers, glioblastomas (GBM), and non-small-cell lung cancer (among others)." (PMID 34205611, 2021). "For instance, the specific PRMT5 inhibitor EPZ015666 has been shown to overcome resistance to mTOR inhibitors in glioblastoma." (PMID 41513606, 2026). "We further demonstrate that SERBP1 regulates mTOR expression in glioblastoma cell lines through G4 elements in the mTOR 5' UTR, and that SERBP1 depletion synergizes with mTOR inhibition to reduce cell growth." (PMID 41846982, 2026). "In glioblastoma multiforme, the combination of artesunate with lower doses of metformin demonstrates antitumor effects by activating the AMPK/mTOR pathway and inducing autophagy in human glioblastoma (U251 and U118-MG) cells." (PMID 40490812, 2025). "In vivo experiments showed that celastrol increased the levels of cleaved Caspase-3, LC3B, and p-JNK, decreased the expression of p-AKT and mTOR, and inhibited the growth of tumors in a mouse glioblastoma in situ transplantation model." (PMID 40061015, 2025).
glioblastoma (continued). "Around 50% of glioblastomas exhibit activating mutations, amplification, or overexpression of EGFR, leading to the activation of downstream PI3K/AKT/mTOR pathways." (PMID 39877641, 2025). "The cytotoxic effect of plinabulin is significantly enhanced when combined with LY294002 (PI3K agonist) and rapamycin (mTOR agonist), confirming its role in promoting glioblastoma cell death by inhibiting the PAM pathway." (PMID 39877641, 2025). "The distinctive function of the PI3K/AKT/mTOR pathway in glioblastoma stem cells (GSCs) has attracted heightened interest owing to its relevance in tumor sustenance, resistance, and recurrence." (PMID 40867215, 2025). "It has been reported that vitexin inhibits cell growth and promotes cell apoptosis by inducing G2/M cell cycle arrest, primarily through the suppression of the Akt/mTOR pathway in human glioblastoma cells." (PMID 40283879, 2025). "As reported in mouse models of pancreatic cancer and glioblastoma, in well-perfused tumor areas, mTOR and eIF4E are active and their inhibition restricts tumor growth." (PMID 40670359, 2025). "The mTOR (mechanistic target of rapamycin) pathway, which regulates oncogenic receptor tyrosine kinase (RTK) signaling, has been studied in glioblastoma (GBM) with EGFR mutations." (PMID 40867316, 2025). "The PI3K/AKT/mTOR pathway is frequently activated across a wide range of cancers, including breast, gastric, ovarian, colorectal, prostate, glioblastoma, and endometrial cancers." (PMID 40362232, 2025). "Desloratadine demonstrated a dual cytotoxic effect by inducing both apoptosis and mTOR/AMPK-dependent autophagy in U251 human glioblastoma cells as well as in primary glioblastoma cell culture." (PMID 41227370, 2025). "In human glioblastoma cell lines U373, H7, and RAEW, elevated MVP levels have been associated with increased invasion via PI3K/AKT/mTOR pathway upregulation." (PMID 40004027, 2025). "The partial reversal by SC79 further supports that these antitumor effects are mediated through inhibition of the EGFR/Akt/mTOR pathway, suggesting that amlodipine holds significant therapeutic potential against glioblastoma via targeting GSCs." (PMID 41145413, 2025). "2, a subunit of the T-type calcium channel, inhibits glioblastoma growth through suppression of the AKT/mTOR pathway and activation of the BAX-mediated apoptotic pathway." (PMID 40535121, 2025). "The results of the N2M2 trial support further investigation of temsirolimus in addition to radiotherapy in patients with newly diagnosed glioblastoma with activated mTOR signaling." (PMID 40913172, 2025). "Key targets include the epidermal growth factor receptor (EGFR), which is often amplified or mutated in glioblastoma, and phosphatidylinositol 3-kinase (PI3K)/Akt/mTOR pathways, critical for cell proliferation and survival." (PMID 39796773, 2025). "For instance, YBX1 has been shown to bind to the 5′-UTR of CCT4 mRNA and promote its translation, thereby facilitating glioblastoma development through mLST8 folding and activation of the mTOR signaling pathway." (PMID 40819060, 2025). "Inhibition of BCAA metabolism promotes glioblastoma cell apoptosis by disrupting mitochondrial dynamics mediated by mitofusin 2 (Mfn2) and inhibiting the PI3K/AKT/mTOR pathway, making it a potential novel therapeutic target for treating glioblastoma." (PMID 40438606, 2025). "Correction to: Glioblastoma induces CAF-like astrocyte activation via the AKT/mTOR-SERPINH1/COL5A1 axis This corrigendum corrects the authors' affiliations to: Jingxian Zhang1,2#, Yajia Chen1,2#, and Hongwu Xu1,2*." (PMID 40819264, 2025). "Schematic representation of the underlying molecular mechanisms by which leech mediates apoptosis and autophagy through SGK1/Caspase‐3 and PI3K/AKT/mTOR pathways to inhibit glioblastoma." (PMID 41326907, 2025). "The cumulative findings strongly indicate that plinabulin manifests its cytotoxic effect in glioblastoma cells through modulation of the PI3K/AKT/mTOR signaling pathway." (PMID 39877641, 2025).
glioblastoma (continued). "In glioblastoma, members of the mTOR-TSC pathway have been found to be acetylated, resulting in the amplification of c-Myc and the promotion of glutaminolysis." (PMID 38279330, 2024). "The overactivation of eIF6 has been confirmed to be associated with tumor proliferation and invasion through the AKT and mTOR pathways in oral squamous cell carcinoma, glioblastoma, and colorectal cancer." (PMID 38238581, 2024). "Previous studies have shown that by inhibiting the PI3K/AKT/mTOR pathway, Vitex induces apoptosis and cell cycle arrest in non-small cell lung cancers and glioblastoma." (PMID 38612399, 2024). "By loading with PI3K-mTOR inhibitor, a promising chemotherapeutic drug for treating glioblastoma, this aptamer-based nano-system demonstrated specific tumor accumulation and mTOR activity inhibition in a mouse model." (PMID 38474636, 2024). "Liu and colleagues investigated the effects of intracranial administration of (Z)-n-butylidenephthalide [(Z)-BP], released via Cerebraca Wafers (CWs), in combination with TMZ to target AXL and mTOR in the glioblastoma framework." (PMID 38391974, 2024). "Cannabinoid-mediated activation of the CB1 and CB2 receptors inhibits the PI3K/Akt/mTOR pathway in glioblastoma cells, which reduces cell growth and promotes apoptosis and autophagy." (PMID 38720772, 2024). "Meanwhile, analysis of differential expression genes (DEGs) enrichment and pathway enrichment revealed that AAA237 would exert anti-glioblastoma effects by regulating the mTOR pathway." (PMID 38341584, 2024). "For example, in mTOR inhibitor-resistant glioblastoma, simultaneous inhibition of mTOR and GLS leads to a synergistic increase in tumour cell death and growth inhibition in mice." (PMID 38699532, 2024). "With our previous study, we also demonstrated the activation of the mTOR pathway in glioblastoma as a resistance mechanism to CDK4/6 inhibition." (PMID 38927958, 2024). "Mammalian target of rapamycin (mTOR) mediates phosphatidyl-inositol-3-kinase (PI3L) signaling, the constitutive activation of which is a hallmark of glioblastoma." (PMID 39794971, 2024). "The results of studies on the mechanism of action of GAL on glioblastoma cells indicate the involvement of the AMPK/mTOR pathway in GAL-induced autophagy through dephosphorylation of mTOR." (PMID 38674891, 2024). "This review describes the regulation of mTOR and the targeting of its complexes in the treatment of cancers, such as glioblastoma, and their stem cells." (PMID 38474373, 2024). "Recent studies have shown that KDELR2 is highly expressed in glioblastoma, mediating the phosphorylation level of mTOR, thereby promoting glioblastoma proliferation." (PMID 39513664, 2024). "As we know, activation of CB1 and CB2 receptors by cannabinoids has been shown to inhibit the PI3K/Akt/mTOR pathway in glioblastoma cells, leading to a decrease in cell proliferation and an increase in apoptosis and autophagy." (PMID 38720772, 2024). "Voxtalisib has demonstrated synergistic effects with low-intensity pulsed ultrasound to inhibit tumorigenesis in glioblastoma’s CSCs while inhibiting PI3K/AKT/mTOR signaling." (PMID 39410026, 2024). "The PI3K/Akt/mTOR signaling cascade, a critical component of the upstream autophagy pathway, is commonly dysregulated and is observed in 90% of glioblastoma (GBM) cases, and is caused by the overexpression of upstream activators, like epidermal growth factor receptor (EGFR)." (PMID 39348350, 2024). "Pathway inhibitors such as everolimus targeting the PI3K/AKT/mTOR pathway are also employed in an attempt to halt glioblastoma multiforme growth." (PMID 38504986, 2024).